EPO (erythropoietin)
Diseases named in the same sentence as EPO in open-access papers (continued):
Sharing a sentence is not in itself a finding about the gene and the disease.
anemia (continued). "Subcutaneous erythropoietin could also be considered in case of severe anemia." (PMID 35243098, 2022). "Even in patients with higher levels of EPO, there may be a chance to recover from anemia by DA therapy if they do not possess ASXL1 mutations." (PMID 35821550, 2022). "Therefore, AmB treatment leads to anemia as a result of EPO (Erythropoietin) suppression." (PMID 36014432, 2022). "Moreover, anemia-induced increase in renal EPO and HIF2A expression were inhibited by Fe treatment." (PMID 35445830, 2022). "Erythropoietin deficiency caused by renal dysfunction may be contributing to anemia, although erythropoietin has not been measured in any patients." (PMID 35628659, 2022). "Indeed, the expression of EPOR has raised concerns about the safety of EPO treatment in cancer patients with anemia because EPO may stimulate cancer cell survival and tumor progression." (PMID 36052260, 2022). "However, taken together, in both, short- and long-acting resistance to EPO, there was estimated particular oxidative disbalance, which could be responsible to EPO-resistant anemia in HD patients." (PMID 35464768, 2022). "Notably, erythropoietin-stimulating agents were efficacious in improving anemia in 59 anemic MF patients treated with ruxolitinib, with an anemia response rate of 54% and minor improvements in Hb levels in an additional 15% of patients, and no thrombotic events reported." (PMID 35877255, 2022). "Inadequate EPO may also be a contributor to the most severe cases of anemia in Tanzanian newborns." (PMID 33995348, 2021). "The appropriate erythropoietin (EPO) response to anemia may be blunted due to kidney dysfunction." (PMID 34453627, 2021). "Erythropoietin (EPO) deficiency and/or resistance, iron deficiencies (resulting from reduced dietary intake, impaired enteral absorption, blood loss), and proteinuria (with loss of transferrin or EPO) are mechanisms leading to anemia development in patients with diabetic kidney disease." (PMID 34708130, 2021). "If the underlying disease and/or anemia are not resolved, iron supplementation therapy and/or treatment with erythropoietin stimulating agents may be considered whereas blood transfusions are an emergency treatment for life-threatening anemia." (PMID 34835988, 2021). "In patients with chronic kidney disease (CKD), anemia develops gradually, primarily due to inadequate renal synthesis of erythropoietin, disturbances in iron balance in the body (which may be in part due to increased hepcidin levels), blood loss, decreased red blood cell survival and inflammation." (PMID 33567688, 2021). "Beyond elevating EPO plasma levels, Roxadustat could correct the degree of anemia by handling iron metabolism and particularly by decreasing hepcidin plasma levels, a response that is independent of the baseline CRP plasma levels and disease state of the CKD patient." (PMID 34830468, 2021). "Therefore, the combination of high-dose recombinant human erythropoietin and oral iron supplements might be a potential choice to manage anemia in patients with colorectal cancer." (PMID 34436045, 2021). "Additionally, there was no information on the causes of anaemia (for example, studies on vitamin B12, folate, erythropoietin levels, or iron) and a neurodegeneration biomarker such as CSF neurofilament light chain or MRI measures of atrophy in this study." (PMID 34794413, 2021). "Indeed, EPO levels were significantly decreased in newborns with the most severe anemia, suggesting that a failed EPO response might actively contribute to fetal anemia." (PMID 33995348, 2021). "If we consider the significant finding in the blood transfusion rate, one hypothesis could be proposed: the combination of high-dose recombinant human erythropoietin and oral iron supplements may not only target the Hb levels, but also reduce anemia-related symptoms." (PMID 34436045, 2021).
anemia (continued). "Second, in patients without iron-deficient anemia, the high dosage of recombinant human erythropoietin could contribute to significantly higher pre-operative Hb concentrations than in patients with iron deficiency." (PMID 34436045, 2021). "We speculate that the degree of fetal anemia observed in Tanzanian newborns may not cause sufficient hypoxia to induce EPO production." (PMID 33995348, 2021). "Considering that EPO is also produced by the liver at embryonic stages or in the case of severe anemia even in adults, we modified a previously reported hepatic differentiation protocol and succeeded in generating EPO-producing cells from hiPSCs (hiPSC-EPO cells)." (PMID 33656639, 2021). "Furthermore, GH insufficiency patients develop anemia with low erythropoietin levels." (PMID 35211089, 2021). "In addition, anemia also occurs in individuals with less severe renal dysfunction in several other disorders, as bone marrow depression, that interfere with the action of erythropoietin and cellular release and utilization of iron." (PMID 32695504, 2020). "Thus, we hypothesized that GABA treatment may improve anemia and increases endogenous EPO levels that stimulates erythropoiesis." (PMID 32290638, 2020). "Last but not least, there is a variety of factors, which may cause a patient not to respond to ESA treatment (extensive bone marrow involvement, a serum erythropoietin level > 500 IU/L, anemia of chronic disease, pure red cell aplasia due to anti-erythropoietin antibodies)." (PMID 33261562, 2020). "In CKD, the mechanism of regulation of EPO secretion in response to the hypoxic stimulus remains fairly long functional, and EPO levels may be normal or even slightly increased, however inappropriately low relative to the degree of anemia." (PMID 33392212, 2020). "However, advances such as avoidance of aluminium (which led to aluminium-induced neurotoxicity secondary to CKD treatment), improved nutrition, improved anemia control (with erythropoietin), have significantly decrease the prevalence of developmental delay in CKD." (PMID 32102670, 2020). "Similar to anemia in EPO−/− mice, iron deficiency anemia did not affect H. pylori colonization." (PMID 33443133, 2020). "Compared with agents commonly used in treating anemia in CKD patients, daprodustat has certain potential advantages, such as avoiding the risk of supraphysiologic EPO levels and improving iron availability, which may reduce the need for iron replacement therapy." (PMID 33597868, 2020). "Consequently, GABA treatment induces a hypoxic environment by altering the energy production pathway, resulting in increased endogenous EPO levels in rats, which might contribute to preventing anemia." (PMID 32290638, 2020). "In addition, they may play an important role in anemia among maintenance dialysis patients combined with insufficient EPO production." (PMID 32318578, 2020). "This could be due to the limited number of patients, but could also suggest distinct mechanisms underlying the impact of EPO on clinical outcomes in patients with or without anemia." (PMID 33330669, 2020). "Anemia in women with CKD is diagnosed when hemoglobin levels are below 12.0 g/dL, and it is associated with insufficient production and release of erythropoietin (EPO), so in most cases, anemia is characterized as being hyperproliferative, normochromic, and normocytic." (PMID 31925336, 2020). "However, HIF-2α is a key regulator of hypoxic EPO induction and could induce a severe anemia when deleted from renal tissue." (PMID 32899941, 2020). "Furthermore, there is an impaired erythropoietin production in response to anemia." (PMID 32481481, 2020). "Moreover, it is possible that such microthrombi could perpetuate AKI, which could lead to disrupted production of erythropoietin, thus exacerbating anisocytosis and/or anemia in patients with COVID-19." (PMID 32825629, 2020).
anemia (continued). "Erythropoiesis-stimulating agents can be used to treat anemia; however, it is unknown whether these agents improve prognosis, and experimental studies indicate that erythropoietin may induce the expression of the vascular endothelial growth factor and stimulate tumor recurrence in mice." (PMID 30719182, 2019). "CKD patients on EPO therapy have shown signs of cardiovascular improvement and reversal of left ventricular hypertrophy, suggesting that correction of anemia may prevent progression of HFpEF." (PMID 31551803, 2019). "Results showed the same relative level of EPO mRNA expression in all exposure groups, both after one month and 8 months of exposure, strongly suggesting that EPO production in the kidney was not implicated in the observed mild anemia." (PMID 31882739, 2019). "EPO is approved for the correction of anemia in patients with chronic renal failure, and its use in renal anemia eliminates the need for red cell transfusions, alleviates the symptoms of anemia, improves survival, reduces cardiovascular morbidity, and enhances the quality of life." (PMID 30866856, 2019). "Standard care for lower-risk 5q deletion [del(5q)] MDS patients with anemia remains supportive, consisting of red blood cell (RBC) transfusions, iron chelation therapy, and treatment with erythropoiesis-stimulating agents (ESAs) in the case of low serum erythropoietin levels." (PMID 31976486, 2019). "Ablation of HIF-2α, and not HIF-1α, was shown to cause anemia that was restored by recombinant EPO." (PMID 31614529, 2019). "Moreover, other confounding factors may have interfered with the correlation of EPO and anemia, which would have contributed to the relatively weak correlations observed in our study, and so had relatively weak correlations between other parameters." (PMID 31183575, 2019). "The increased production of EPO may be attributable to the response of EPO to anaemia or hypoxia." (PMID 30894794, 2019). "Although the guidelines for the treatment of anemia in patients with CKD favor a relatively liberal use of intravenous iron with the purpose of strengthening the action of erythropoietin (EPO), they fail to consider that high ferritin levels may induce hemosiderosis." (PMID 31441929, 2019). "Given that our analysis did not detect any correlation between the studied EPO SNPs and the presence/absence of anaemia (data not shown), it is plausible that inflammation, a key emerging risk factor for T2D, is a potential mechanism linking EPO and mortality in T2D patients." (PMID 31316151, 2019). "Considering that EPO is clinically used as chronic treatment against anemia, we used here the Tg6 mouse model that constitutively overexpresses human EPO in an oxygen-independent manner, to examine the consequences of long-term EPO therapy on mineral and bone metabolism." (PMID 31628396, 2019). "In addition, plasma EPO is usually increased in response to anemia and hypoxemia." (PMID 31183575, 2019). "Indeed, indomethacin by reducing cytokine production and inflammation, may improve by itself anemia and increase responsiveness to EPO treatment." (PMID 30294279, 2018). "Moreover, l-carnitine administration has been reported to be effective in increasing the red blood cell lifespan through improvement of the erythrocyte membrane fat metabolism, improvement of erythrocyte cell membrane stabilization, and erythropoietin low-responsiveness anemia in renal diseases." (PMID 29616582, 2018). "However, in CKD there is no clear inverse correlation between anemia degree and EPO serum levels, suggesting that other mechanisms are of importance beyond EPO deficiency." (PMID 29738538, 2018). "Our current studies verified the hematopoietic function of JPYS by regulating EPO expression via hypoxia-inducible factor-1α in kidney cells, suggesting that JPYS could be employed as an alternative medicine for the treatment of CKD associated-anemia." (PMID 29615029, 2018).
anemia (continued). "Moreover, a number of studies have demonstrated recombinant human EPO (rhEPO), also known as erythropoiesis stimulating agents (ESAs) which have been widely used to relieve chemotherapy-induced anemia may enhance tumor progression or decrease patient survival." (PMID 29137269, 2017). "The pathophysiology of anemia in cancer is complex and has been attributed to inflammation that leads to increased levels of cytokines that impair the production of hematopoietic growth factors, including erythropoietin, and the bone marrow response to erythropoietin." (PMID 28327200, 2017). "Moreover, routine haemoglobin levels testing during treatment, and correction of anaemia with concomitant administration of erythropoietin, could be of significant importance as it seems to directly affect patients’ outcome." (PMID 29108271, 2017). "Hypoxia-induced factor (HIF) pathway has been intensively investigated in kidney disease, especially in chronic kidney disease (CKD), as research has shown that HIF-mediated erythropoietin (EPO) synthesis might work as a potential therapeutic strategy for managing CKD-related anemia." (PMID 29404328, 2017). "The erythropoietin (EPO) resistance of the erythron or renal EPO deficiency may be present, such that recombinant human erythropoietin (rhEPO) therapy should be considered as add-on therapy for anemia." (PMID 29348938, 2017). "Linear regression analysis showed that erythropoietin levels in chronic kidney disease, anemia of chronic disease and anemia of unknown etiology were lower by 48%, 46% and 27%, respectively, compared to iron deficiency anemia even after adjusting for hemoglobin, eGFR and comorbidities." (PMID 27310832, 2016). "Finally in consequence of these pleiotropic EPO effects it is thought that timely correction of anemia may lead to a significant improvement in the cardiovascular outcome in CKD patients." (PMID 27034745, 2016). "Erythropoietin deficiency has also been suggested as a mechanistic link between anemia and cognitive decline, based on animal models demonstrating erythropoietin receptors in the brain and uncontrolled clinical studies of patients treated with erythropoietin stimulating agents." (PMID 26823182, 2016). "Also anaemia is common in these patients due to a reduction in renal erythropoietin production." (PMID 26419852, 2016). "Thus, erythropoietin increases the risk of tumor progression in colon cancer and should not be used to treat anemia in this type of cancer." (PMID 27543111, 2016). "In addition, it has been reported that EPO administration does not improve anemia in patients with TMPRSS6 mutations." (PMID 26845567, 2016). "Elevated EPO levels were observed in the TB group, implying that the response to anemia was not impaired in this mouse model; therefore, EPO production might increase as a compensatory response to the anemia status." (PMID 27068103, 2016). "Although EPO production and RBC counts were elevated in the TB group, anemia with decreased Hb levels was observed; therefore, disturbance of iron metabolism might be the underlying cause of the anemia observed in the LC-06-JCK model." (PMID 27068103, 2016). "Anemia causes hypoxia due to decreased hemoglobin level, and there are several nonhemodynamic (increased erythropoietin production, decreased affinity of hemoglobin for oxygen due to an increase in 2,3-diphosphoglycerate) and hemodynamic compensatory mechanisms." (PMID 25710019, 2015). "When extrapolated to humans, our study suggests that the use of EPO for the treatment of anemia in patients with chronic renal disease might impair the control of fungal infections such as those caused by Hc, leading to lung inflammation, tissue damage, and death." (PMID 26538835, 2015). "Consequently, we cannot evaluate if the elevated EPO concentrations are a consequence of anemia." (PMID 25793991, 2015). "These high EPO levels might be the first sign of a subclinical disease or an “anemia of aging”." (PMID 25915923, 2015).
anemia (continued). "However, several lines of evidence strongly argued against the hypothesis that anemia of hypothyroidism is to be exclusively attributable to insufficient EPO levels." (PMID 26779261, 2015). "If we assume that IGF-1 plays an anti-inflammatory effect, decreased IGF-1 concentrations may account for the increased levels of inflammatory molecules, which are known to negatively affect EPO secretion and red cell precursor survival, ultimately resulting in anemia." (PMID 26779261, 2015). "In response to anemia, we administered EPO based on individual decisions as follows: (i) if patients were symptomatic or (ii) if we assumed that RBV dose reduction could be avoided or (iii) if we assumed that we would have to reduce RBV dosing to a lesser extent when applying EPO." (PMID 25889921, 2015). "Moreover, we speculated that prior administration of erythropoietin (EPO) would blunt the anemia by stimulating young RBC production." (PMID 26390038, 2015). "However, LLC-bearing mice are hyporesponsive to EPO since the severe anemia could only partially be corrected, possibly due to inflammation that antagonizes erythropoiesis and/or excessive erythrocyte cytolysis." (PMID 26636649, 2015). "Interestingly, there is a case reported of a patient who underwent liver transplantation, started antiviral therapy for hepatitis C with ribavirin and interferon, received recombinant erythropoietin for anemia, but developed anti-erythropoietin antibody-mediated PRCA while on immunosuppression." (PMID 26240773, 2015). "EPO-induced breast cancer cell migration was blocked by the PARP inhibitor Veliparib (ABT-888), suggesting an essential role for polyADP-ribosylation in this process and suggesting a new cancer-associated anemia treatment modality with combined administration of EPO and PARP inhibitors." (PMID 25426117, 2014). "However, HbA1c values are strongly influenced by anemia and erythropoietin (EPO) treatment." (PMID 25386190, 2014). "Moreover, most of our patients had anemia and were treated with erythropoietin." (PMID 25086644, 2014). "Furthermore, a previous study demonstrated that, to prevent the detrimental effects of EPO, the treatment of anemia in chronic renal failure usually requires low doses of EPO between 350 and 400 units or less on a very repetitive base over several weeks or months." (PMID 24503957, 2014). "In hemodialysis (HD) patients requiring anemia management, the 3-fold longer terminal half-life (25.3 hours) of darbepoetin-alpha (DA) results in reduced dose frequency when compared with recombinant human erythropoietin (EPO) -alpha or -beta by intravenous administration (8.5 hours)." (PMID 24384988, 2013). "In several studies which was conducted so far, it was not concluded that treatment of anemia caused by CKD with recombinant human erythropoietin could improved the renal function and reduced need to dialysis." (PMID 25340147, 2013). "Furthermore, the use of anti-EPO auto-antibodies as a therapy in murine malaria studies, is an indication of the important role it may play in severe malaria anaemia." (PMID 23978045, 2013). "Anaemia is promoted by erythropoietin deficiency, shortened existence of red blood cells, death of immature erythroblasts due to the Fas ligand and TRAIL, decreased responsiveness of the erythron to proliferative signals of erythropoietin, and the myelosuppressive effect of the chemotherapy." (PMID 24385802, 2013). "Indeed, inadequate EPO production and EPO resistance are contributor of anemia in SLE." (PMID 25340141, 2013). "While malnutrition-inflammation syndrome may play a central role in poor clinical outcome, including a high rate of mortality, diminished quality of life and hospitalization, it may also lead to high level of ferritin and refractory anemia including unresponsiveness to EPO in these patients." (PMID 25340139, 2013).